NLGN3 (neuroligin 3)
Diseases named in the same sentence as NLGN3 in open-access papers (continued):
Sharing a sentence is not in itself a finding about the gene and the disease.
glioma (continued). "Notably, basal glioma cell growth (by complete medium, no NLGN3) was also inhibited by Gαi1/3 DshRNA." (PMID 34373757, 2021). "Thus, we speculate that primary gliomas mostly occur in the cortex and postoperative recurrence of GBM mainly in deep brain regions may have a strong correlation with NLGN3 levels, because NLGN3 is necessary for gliomas' growth." (PMID 29777576, 2018). "The key role of NLGN3 in promoting glioma growth is supported also by the observation that transplanted glioma cells can grow in the brains of mice that express NLGN3, but not in the brains of mice lacking NLGN3 expression." (PMID 30279357, 2018). "NLGN3 expression in GBM is inversely correlated with patient survival, and neuron–glioma interactions promote glioma proliferation through synaptic and non-synaptic mechanisms." (PMID 40143161, 2025). "In response to NLGN3, multiple RTKs (VEGFR2, EGFR and FGFR1) as well as Gαi1 and Gαi3 were enriched in the endosomal fraction in P1 glioma cells, but not in Gαi1/3-silenced cells." (PMID 34373757, 2021).
autism spectrum disorder (37 papers, 2009 to 2026). A spectrum of developmental disorders that includes autism, and Asperger syndrome. "Neuroligin-3 (NLGN3) was first identified as a risk gene associated with autism spectrum disorder (ASD)." (PMID 41929011, 2026). "Mutations in the Neuroligin-3 (Nlgn3) gene are implicated in autism spectrum disorder (ASD) and gastrointestinal (GI) dysfunction, but cellular Nlgn3 expression in the enteric nervous system remains to be characterised." (PMID 37509099, 2023). "A gain of function of Nlgn3 resulting in inhibition of synaptic transmission is associated with a model for autism spectrum disorders." (PMID 37759530, 2023). "Mutations in the postsynaptic transmembrane protein neuroligin-3 are highly correlative with autism spectrum disorders (ASDs) and intellectual disabilities (IDs)." (PMID 35850732, 2022). "A study of Neuroligin-3 (NL3) mutated mice, who exhibit autism spectrum disorder symptoms, led to the discovery that the D1 MSNs in the NAc show reduced synaptic inhibition compared to excitation." (PMID 29593596, 2018). "Here we explore the possibility that mixed-group housing of mice carrying a deletion of Nlgn3, a gene associated with autism spectrum disorders, and their wild-type littermates induces changes in each other’s behavior." (PMID 28795135, 2017). "The first two mutations involved in autism spectrum disorder identified in genes encoding neuroligins were a C to T transversion in NLGN3, which originated an Arg451Cys change, and a T insertion in NLGN4 that generated an Asp396X stop codon." (PMID 22723984, 2012). "The R451C change in NLGN3, which has been related to autism spectrum disorder, was shown to cause the retention of the protein in the endoplasmic reticulum." (PMID 22723984, 2012). "The question arises of how our findings may relate to NLGN3 mutations observed in patients with autism spectrum disorders (ASDs)." (PMID 39003414, 2025). "We identified 15 DEGs after the deletion of astrocytic Nlgn3 deletion and, interestingly, those DEGs in the V1 cortex are distinct from the DEGs observed in the cerebellum and are enriched in functions associated with autism spectrum disorder." (PMID 39003414, 2025). "Although, NLGN3 gene is known as a risk gene for neurodevelopmental disorders such as autism spectrum disorder (ASD) and intellectual disability (ID), the pathogenic contribution of the canonical NLGN3-NRXN and noncanonical NLGN3-PTPδ pathways to these disorders remains elusive." (PMID 38475840, 2024). "NLGN3 belongs to the neuroligin family, a class of postsynaptic cell adhesion molecules that regulate synapse organization and dendritic outgrowth, and NLGN3 missense variants have previously been associated with autistic spectrum disorder (ASD)." (PMID 36810932, 2023). "Neuroligin-3 (Nlgn3), a neuronal adhesion protein implicated in autism spectrum disorder (ASD), is expressed at excitatory and inhibitory postsynapses and hence may regulate neuronal excitation/inhibition balance." (PMID 34845591, 2022). "Intriguingly, Nlgn3 has been implicated in autism spectrum disorder (ASD) in mutation screenings." (PMID 34845591, 2022). "The consequences of increased Nlgn3 transcript remain unclear, but Nlgn3 is implicated in a number of behavioral impairments, such as autism spectrum disorders (ASD)." (PMID 35955861, 2022). "Nlgn3 is also associated with non-syndromic autism spectrum disorder (ASD), which is characterized by challenges with social communication and restricted behaviors due to unknown etiology." (PMID 34690695, 2021). "Mutations of Neuroligin 3 (NLGN3) have been associated with autism spectrum disorder (ASD)." (PMID 33758193, 2021). "In fact, a study on Nlgn3-deficient mice revealed that the elimination of this gene could lead to several symptoms linked to autism spectrum disorder, including alterations in social memory; this result is in line with previously published results in the literature." (PMID 33925709, 2021).
autism spectrum disorder (continued). "In a study involving a mouse model of autism spectrum disorder (neuroligin 3 R451C knockin mice), d-Cycloserine (DCS, a partial agonist that binds at the same site as D-serine) was found to improve PV dysfunction." (PMID 37311798, 2023). "Mutations in neuroligin genes, including the arginine to cystein substitution at the 451st amino acid residue (R451C) of neuroligin-3 (NLGN3), have been identified in patients with autism spectrum disorder (ASD)." (PMID 34262438, 2021). "Numerous studies have linked genetic deficits of NLs, especially neuroligin 3 (NL3), to autism spectrum disorders (ASDs)." (PMID 31849609, 2019). "Two specific point mutations in NLGN3 and NLGN4 genes, involved in autistic spectrum disorder, were further characterized in this experimental system." (PMID 22723984, 2012). "Synaptic genes, NLGN3 and NLGN4X, two homologous members of the neuroligin family, have been supposed as predisposition loci for autism spectrum disorders (ASDs), and defects of these two genes have been identified in a small fraction of individuals with ASDs." (PMID 21569590, 2011). "Additionally, multiple mutations in NLGNs have been identified in patients with autism spectrum disorders (ASD), including the first gene mutation linked to ASDs, namely the NLGN3 arginine-451 to cysteine (R451C) point mutation." (PMID 39775628, 2025). "Critically, these morphological effects were not induced by autism spectrum disorder (ASD)-associated NLGN3/4X variants." (PMID 34542148, 2022). "The mRNA expression levels of NLGN3 and SHANK3 were found to be significantly decreased in individuals with autism spectrum disorder (ASD) compared to the controls." (PMID 33672431, 2021).
glioblastoma (15 papers, 2018 to 2025). The most malignant astrocytic tumor (WHO grade IV). "Previous research has firmly established that higher levels of NLGN3 mRNA and protein, derived from tumors, are inversely linked to the survival rates of adult glioblastoma patients." (PMID 39469896, 2024). "In the deep brain region, a high expression of NLGN3 was associated with glioblastoma recurrence." (PMID 33969375, 2021). "Among the post-synaptic genes expressed in glioblastoma cells leading to tumor progression, the NLGN-3 pathways were confirmed to have a key role." (PMID 37511496, 2023). "In both patient-derived and commercial glioblastoma cells, depleting Gαi1/3 effectively inhibits the NLGN3-induced activation of cellular proliferation and migration mechanisms." (PMID 37511496, 2023). "This evidence has opened the way for different approaches to targeting the NLGN3-dependent altered synaptogenic activity of glioblastomas." (PMID 37511496, 2023). "Glioblastoma proliferation, invasion, and resistance to apoptosis are promoted by the binding of TrkB receptors on glioblastoma cells to molecules released from neurons such as brain-derived neurotrophic factor (BDNF) and neuroligin-3 (NLGN3)." (PMID 41208963, 2025). "In Glioblastoma, ADAM10 promote tumor progression by several proposed mechanisms, including Neuroligin-3 release, cleavage of N-cadherin, and depression of NK cell activation." (PMID 36922678, 2023). "Cleavage of NLGN1 and NLGN3 has been previously studied with important functional implications of the extracellular domain (ECD) cleavage byproduct of NLGN3 serving as a mitogen for glioblastoma in the brain." (PMID 39766868, 2024).
Intellectual disability (15 papers, 2011 to 2025). "Patients with SOX11 syndrome have intellectual disability, patients with loss-of-function variants in NLGN3 have developmental delay and autistic spectrum disorders, and those with cerebellar hypoplasia and intellectual disability are associated with recessive variants in the PRDM13 gene." (PMID 38436980, 2024). "Comorbidities: intellectual disability (30%), epilepsy (20%−30%) Risk: older parents, genetic mutations (e.g., SHANK3, NLGN3)." (PMID 40521363, 2025). "By interrogating GeneMatcher, we found an additional NLGN3 LoF variant in an unrelated patient with phenotypic features of GD and ASD with intellectual disability (Case 2)." (PMID 36810932, 2023). "Recent studies have identified many mutations in the genes encoding neuroligins (e.g., R451C for NLGN3 and a frame shift insertion mutation for NLGN4) linked to patients with ASD, intellectual disability, and schizophrenia." (PMID 32443651, 2020). "The sex-linked genes, NLGN3 and NLGN4, are both on the X chromosome and were among the first few genes to be linked with ASD and intellectual disability (ID)." (PMID 32848696, 2020). "A rare mutation of two X-linked neuroligin genes, neuroligin 3 (NLGN3) and neuroligin 4X (NLGN4X) are most prevalent in non-syndromic X-linked ASD and intellectual disability (ID)." (PMID 39408797, 2024).
Asperger syndrome (9 papers, 2012 to 2024). "A study identified a frameshift de novo mutation, 1186insT in NLGN4, in two siblings with ASD and Asperger syndrome in a Swedish family, and that linked NLGN3 and NLGN4 to ASDs." (PMID 31185809, 2019). "Of these, OPHN1, IGBP1, DLG3, NLGN3, and ZDHHC15 are associated with mental retardation or Asperger syndrome phenotypes." (PMID 24778889, 2014). "By screening for NLGN3 and NLGN4X mutations in subjects with ASD or Asperger syndrome (a type of ASD with higher cognitive ability and normal language), one study of 140 males and 18 females identified two affected brothers; one has ASD and another has Asperger syndrome in one Swedish family." (PMID 27992373, 2017). "In addition to ASD, there are some reports indicating that NLGN3 and NLGN4X are also relevant to Asperger syndrome, X-linked mental retardation, and Tourette syndrome." (PMID 22934180, 2012). "In addition, a similar genetic phenomenon of NLGN3 was found in another Swedish family in two brothers with ASD and Asperger syndrome, respectively." (PMID 27992373, 2017).
schizophrenia (6 papers, 2011 to 2021). A major psychotic disorder characterized by abnormalities in the perception or expression of reality. "Missense mutations in NLGN2 or NLGN3 have been associated with several neuropsychiatric diseases, such as schizophrenia and autism." (PMID 33343614, 2020). "Taken together, these findings suggest that NLGN2 and NLGN3 mutations are part of the genetic underpinnings of schizophrenia and support the implication of synaptic dysfunction in schizophrenia pathogenesis." (PMID 33343614, 2020). "A rare loss-of-function mutation of Nlgn3, which can cause a premature stop 42 codons downstream of the frameshift mutation in exon 2, was also found among a study of 273 people diagnosed with schizophrenia." (PMID 34690695, 2021). "Mutations in the genes of several components of this complex, especially Shank3 and Neuroligin 3 and 4, are linked to several genetic-associated neurodevelopmental disorders, in particular, ASD and schizophrenia." (PMID 30586380, 2018). "Interestingly, glial progenitor cells from individuals with schizophrenia express significantly lower levels of Nlgn1, Nlgn2, and Nlgn3 mRNA compared with controls, suggesting a role for glial Nlgn3 protein in pathophysiological conditions." (PMID 34690695, 2021). "We next measured NLGN3 and SHANK3 mRNA expression levels in immortalized lymphoblastoid cells from 45 patients with schizophrenia and 45 healthy controls to examine the disease specificity of the differential expression levels between patients and healthy controls." (PMID 21615902, 2011). "Our study reveals reduced levels of NLGN3 and SHANK3 mRNA expression in lymphoblastoid cell lines derived from individuals with ASD, but not from those of individuals with schizophrenia." (PMID 21615902, 2011).
brain tumors (5 papers, 2018 to 2024). "Paracrine signaling through soluble factors such as brain-derived neurotrophic factor (BDNF), 78 kDa glucose-regulated protein (GRP78), and neuroligin-3 (NLGN-3) is another route of communication in brain tumor networks." (PMID 36831383, 2023).
epilepsy (4 papers, 2014 to 2026). A brain disorder characterized by episodes of abnormally increased neuronal discharge resulting in transient episodes of sensory or motor neurological dysfunction, or psychic dysfunction. "Neuroligin-3 showed a protective effect on memory performance in all patients, not modified by epilepsy." (PMID 42291752, 2026).
optic pathway glioma (4 papers, 2022 to 2025). Optic pathway glioma (OPG) is a benign tumor that develop along the optic nerve (chiasm, tracts, and radiations) characterized by impairment or loss of vision and may be accompanied by diencephalic symptoms such as reduced growth and alteration in sleeping patterns. "In addition to the critical contributions from immune system cells, we have recently shown that NF1 mutation in neurons synergizes with light-induced retinal ganglion cell activity to regulate neuroligin-3 (NLGN3) shedding and Nf1-optic pathway glioma (Nf1-OPG) initiation and growth." (PMID 35589737, 2022).
Anxiety (3 papers, 2014 to 2022). Intense feelings of nervousness, tension, or panic often arise in response to interpersonal stresses. "Here, we show that male mice lacking Nlgn3 are socially submissive to their wild-type littermates and that this social submission correlates with increased anxiety in Nlgn3 knockout mice." (PMID 28795135, 2017). "Moreover, social submission in adult male Nlgn3 knockout mice correlated with an increase in their anxiety." (PMID 28795135, 2017). "Note that in measures of anxiety, the Nlgn3+/– mice raised with Nlgn3–/– mice were indistinguishable from Nlgn3+/– mice raised with Nlgn3+/+ littermates, suggesting that the behavior of Nlgn3–/– mice does not affect the anxiety of their littermates." (PMID 28795135, 2017).
breast cancer (3 papers, 2023 to 2025). A primary or metastatic malignant neoplasm involving the breast. "Collectively, the in vitro findings suggest the role of ANK2 and NLGN3 in breast tumorigenesis suggesting it may be a potential drug target for breast cancer therapeutics." (PMID 38977697, 2024). "Our findings were further validated using qRT-PCR, western blotting and immunohistochemistry which show decreased expression of NLGN3, MAML2, ANK2, and SYNE1 in breast cancer cell lines as MCF7 and MDA-MB-231 as compared to control cell line MCF10A." (PMID 38977697, 2024). "The unpaired student’s t-test showed the decrease in protein expression of ANK2, SYNE1 and NLGN3 was significant in the cancer cell lines MDA-MB-231 (p-value < 0.05) when compared with control MCF10A and decrease in protein expression of SYNE1 was significant in MCF7 breast cancer cell line." (PMID 38977697, 2024).
cognitive decline (3 papers, 2023 to 2024). "In temporal lobe epilepsy models, PBM has been observed to mitigate neurodegeneration and cognitive decline by upregulating synaptic-related proteins, such as neuroligin-3, indicating its role in enhancing synaptic connectivity and cognitive function." (PMID 39246604, 2024). "Our findings demonstrate that PBM attenuates epileptic excitotoxicity, neurodegeneration and cognitive decline induced by TLE through inhibition of the Nlgn3 gene decrease induced by excitotoxicity." (PMID 36635704, 2023). "After applying PBM to a temporal lobe epilepsy model, neurodegeneration and cognitive decline were attenuated by increasing the expression of the synapse-related protein neuroligin-3." (PMID 37895108, 2023).
fragile X syndrome (3 papers, 2021 to 2023). A genetic syndrome caused by mutations in the FMR1 gene which is responsible for the expression of the fragile X mental retardation 1 protein. "Translation of the mRNAs for NLGN1, NLGN2, and NLGN3 is negatively regulated by Fragile X mental retardation protein (FMRP), loss of this translational repressor, FMRP, leads to Fragile X syndrome, associated with ASD." (PMID 37807632, 2023).
diabetes (2 papers, 2022 to 2024). "In our studies, the expression levels of NLGN2 and NLGN3 were elevated in the maternal diabetes-related streptozotocin-induced ASD mouse model, which may be a response to the increased oxidative stress." (PMID 36479216, 2022).
malignant glioma (2 papers, 2017 to 2024). A grade III or grade IV glioma arising from the central nervous system. "For example, electrically active neurons release Neuroligin-3 (NLGN3), a mitogen for malignant glioma cells, which are believed to be derived from and closely related to OPs." (PMID 28608780, 2017).
mental disorder (2 papers, 2013 to 2020). A disease that has its basis in the disruption of mental process. "Similar contrasting effects on learning and memory paradigm have been observed in other knockout models for example Shank 1 and Neuroligin-3 knockout mice and alternation between enhancement and deficits in learning and memory is a feature bearing relevance to certain mental disorders." (PMID 23560106, 2013).
Rett syndrome (2 papers, 2018 to 2021). A severe neurodevelopmental disorder affecting the central nervous system.
brain injury (1 paper, 2023). Acute and chronic (see also brain INJURIES, CHRONIC) injuries to the brain, including the cerebral hemispheres, CEREBELLUM, and brain STEM. "Conversely, neuronal overexpression of NLGN3 increased Akt activation and alleviated MCAO-induced ischemic brain injury in mice." (PMID 37880221, 2023).
Cerebral ischemia (1 paper, 2023). Restriction of arterial blood supply to the brain associated with insufficient oxygenation to support the metabolic requirements of the tissue. "We first examined whether NLGN3 cleavage and expression were altered in the brain tissues with cerebral ischemia/re-perfusion." (PMID 37880221, 2023).
hypogonadism (1 paper, 2023). A disorder characterized by decreased function of the gonads. "Notably, the second patient identified in this study (Case 2) is also hemizygous for a nonsense NLGN3 variant and, although prepubertal, displayed typical red flag signs of hypogonadism, including small testes volume and micropenis." (PMID 36810932, 2023).